HERC4 (HECT and RLD domain containing E3 ubiquitin protein ligase 4)
Diseases named in the same sentence as HERC4 in open-access papers (continued):
Sharing a sentence is not in itself a finding about the gene and the disease.
tumor (6 papers, 2013 to 2025). "Mechanistically, the anti-tumor activity of Androg essentially relied on the reduction in host cell proteins, which are associated with ubiquitin-mediated proteolysis pathways, particularly HERC4 and SMURF2." (PMID 34202736, 2021). "HERC4, a potential E3 ubiquitin-protein ligase, shows contradictory roles, acting as an oncogene or a tumor suppressor." (PMID 40429863, 2025). "HERC4 is a new E3 ligase for the tumor suppressor LATS1 and destabilizes LATS1 by promoting the ubiquitination of LATS1." (PMID 30710319, 2019). "Receiver operating characteristic (ROC) analysis was applied to determine the optimal cut-off score for positive expression of HERC4, when HERC4 positive expression percentage was above 60%, tumor was defined as “positive”." (PMID 24225229, 2013). "We introduced a scoring system method based on percentage of positive staining tumor cells to assess HERC4 immunoreactivity." (PMID 24225229, 2013). "We can hypothesize that a potential role of CBD in the inhibition of tumor growth may involve the modulation of ubiquitin ligase activity, including HERC4." (PMID 40429863, 2025). "Notably, these alterations in tumor suppression were consistent with that the protein levels of both MafA and HERC4." (PMID 37028761, 2023). "Moreover, in mammals HERC4 has been described as tumor suppressor in non-small cell lung cancer (NSCLC) able to control SMO protein stability." (PMID 32531973, 2020). "Thus, we selected the cut-off score according to clinical stage and defined tumor as HERC4 positive when HERC4 expression percentage was above 60%." (PMID 24225229, 2013). "In human NSCLC, HERC4 knockdown activates HH signaling and promotes NSCLC cell proliferation thus standing as a tumor suppressor." (PMID 32531973, 2020).
infection (5 papers, 2017 to 2022). The state of being infected such as from the introduction of a foreign agent such as serum, vaccine, antigenic substance or organism. "For Ssa18, the most significant SNPs overlap with the probable E3 ubiquitin-protein ligase HERC4, which is up-regulated in response to infection at both 7 and 14 dpi." (PMID 33985436, 2021). "The closest gene to this putative QTL showing expression differences is the probable E3 ubiquitin-protein ligase HERC4 (HERC4), up-regulated both at 7 and 14 days post infection." (PMID 33985436, 2021). "Of the genes participating in metal ion binding (MIB1, KAT6B, ITGA8, HBAC, KCNC1, and F13A), most were downregulated during the later stages of GCRV infection, whereas genes involved in protein ubiquitination (HERC1 and HERC4) were upregulated during the later stages of infection." (PMID 28906455, 2017). "HERC1 and HERC4 are probable E3 ubiquitin-protein ligases involved in ubiquitin-mediated protein degradation, and upregulation of these genes during the later stages of infection suggested that protein degradation occurred." (PMID 28906455, 2017).
HERC4 also shares sentences with these, for which no sentence is quoted: breast tumor (2 papers); cataract (1); cervical cancer (1); Fibroadenoma (1); intraductal carcinoma (1); Parkinson disease (1); triple-negative breast carcinoma (1); viral infection (1).